IGFBP3 (insulin like growth factor binding protein 3)
Diseases named in the same sentence as IGFBP3 in open-access papers (continued):
Sharing a sentence is not in itself a finding about the gene and the disease.
astrocytoma (3 papers, 2015 to 2021). "In addition, we reproduced the increase in IGFBP-3 after treatment with Aβ using human astrocytoma cell lines and found that IGFBP-3 was expressed via calcineurin." (PMID 26637371, 2015). "To determine whether Aβ treatment upregulates the transcription of IGFBP-3, we treated human astrocytoma cells (H4 cells) with 1 μM Aβ1–42 for 24 h." (PMID 26637371, 2015).
autism (3 papers, 2012 to 2022). Persistent deficits in social interaction and communication and interaction as well as a markedly restricted repertoire of activity and interest as well as repetitive patterns of behavior. "Based on its role in neurogenesis, Igfbp3 has been linked to the involvement in certain disease processes, such as ischemia, hypoxia and autism." (PMID 22701680, 2012). "Reduced excretion might be due to increased binding of IGF-1 by the IGF-1 binding protein, insulin-like growth factor binding protein 3 (IGFBP-3) that is increased in blood from autism patients." (PMID 35962006, 2022).
bladder tumour (3 papers, 2020 to 2025). "Noteworthy, it was previously shown that CA IX expression in human bladder tumour cells negatively correlates with IGFBP3 mRNA, thus supporting the results of this study." (PMID 32210366, 2020). "However, some m6A regulators, including METTL3, RBM15B, YTHDF1, YTHDF2, and IGFBP3, were significantly overexpressed in bladder tumors, and some m6A regulators, including METTL14, METTL16, ZC3H13, and YTHDF3, were markedly downregulated in bladder tumors." (PMID 35004726, 2021). "We found that seven of these genes, IGFBP3, VEGF, CCNG2, NDRG1, PFKFB3, ADM and SLC2A1, were also upregulated in MIBC and/or NMIBC in our study, suggesting parallel hypoxia-induced expression changes with primary bladder tumour tissue." (PMID 40867253, 2025).
bronchopulmonary dysplasia (3 papers, 2012 to 2025). Bronchopulmonary dysplasia is a chronic respiratory disease that results from complications related to lung injury during the treatment of infant acute respiratory distress syndrome in low-birth-weight premature infants or from abnormal lung development in older infants. "In a phase‐2 trial involving extremely preterm infants (delivered < 28 weeks), systemic IGF‐1/IGFBP‐3 therapy led to a decrease in the occurrence of severe bronchopulmonary dysplasia and a non‐significant decrease in moderate‐to‐severe intraventricular hemorrhage." (PMID 40580544, 2025). "Mean (SD) IGF-II, IGFBP-1, IGFBP-3 and ALS levels at postmenstrual age (PMA) 30-33 weeks are shown for infants with and without bronchopulmonary dysplasia (BPD)." (PMID 22924869, 2012).
chronic pancreatitis (3 papers, 2011 to 2016). A chronic inflammatory process causing damage and fibrosis of the pancreatic parenchyma. "This study demonstrated that three genes, IGFBP3, SPINK1 and PSCA, can differentiate, in tissue samples, cancerous samples from benign samples (normal and chronic pancreatitis cases)." (PMID 21245863, 2011).
colon adenocarcinoma (3 papers, 2017 to 2024). "Using the EPIC, MCPCOUNTER, XCELL, and TIDE algorithms, we found that IGFBP3/4/5/6/7 were all associated with cancer-associated fibroblast (CAF) infiltration in STAD, COAD (colon adenocarcinoma), and READ (rectal adenocarcinoma)." (PMID 34745945, 2021). "Finally, IGFBP3–7 were all associated with cancer-associated fibroblast infiltration in STAD, colon adenocarcinoma, and rectal adenocarcinoma." (PMID 34745945, 2021).
colorectal adenoma (3 papers, 2008 to 2024). An adenoma that arises from the colon or rectum. "We evaluated the association between tissue or plasma IGFBP-3 and risk of colorectal adenomas or low apoptosis." (PMID 18498652, 2008). "In some studies, elevated plasma IGF-I was associated with increased risk of colorectal adenomas while inverse associations were reported for plasma IGFBP-3." (PMID 18498652, 2008). "Our findings that reduced expression of tissue IGFBP-3 mRNA in the normal colon is associated with increased risk of colorectal adenomas are compatible with evidence in experimental animal models indicating that elevated tissue IGFBP-3 protects against colon carcinogenesis." (PMID 18498652, 2008). "In the study reported here, we evaluated the associations of plasma IGFBP-3, and local IGFBP-3 mRNA expression with colorectal adenomas or apoptosis in normal colonic mucosa." (PMID 18498652, 2008). "In summary, we found that tissue IGFBP-3 but not plasma IGFBP-3 was associated with modestly elevated risk of colorectal adenomas." (PMID 18498652, 2008).
dry eye (3 papers, 2020 to 2024). "In the present study, we sought to interrogate the role of IGFBP-3 in mitochondrial and metabolic activity in response to hyperosmolar stress in vitro and in a mouse model of aqueous-deficient dry eye in vivo." (PMID 35409425, 2022). "However, studies are needed to evaluate the impact of reflex tearing and dry eye on tear levels of IGFBP-3, and to determine its sensitivity and specificity compared to hemoglobin A1c." (PMID 32194500, 2020). "According to previous research, the Insulin-like Growth Factor Binding Protein-3 (IGFBP-3) can restore mitochondrial function in hyperosmotic models of corneal epithelial cells, alleviating dry eye symptoms." (PMID 38725011, 2024).
emphysema (3 papers, 2006 to 2018). "Increased Igfbp3 expression is associated with emphysema and senescent fibroblasts, where it results in Igf1 sequestration and reduced cell proliferation." (PMID 19804646, 2009). "The upregulation of the senescence-associated IGFBP-3 and -rP1 in emphysema suggests that inhibition of the action of insulin and insulin-like growth factors could be involved in the reduced in vitro-proliferation rate." (PMID 16504044, 2006). "Primary lung fibroblasts harvested from patients with emphysema are senescent, which express higher levels of IGFBP-3 mRNA and protein than those from controls." (PMID 30018981, 2018). "The upregulation of IGFBP-3 and -rP1 can be taken as further evidence for a senescent phenotype in emphysema." (PMID 16504044, 2006). "In line with the gene expression we found increased cell culture supernatant concentrations of IGFBP-3 (p = 0.006) in emphysema." (PMID 16504044, 2006). "After normalizing for the amount of total protein, the median (quartiles) concentration of IGFBP-3 was 1619.6 (1024.1;2937.0) pg/mg protein in emphysema and 505.8 (288.9;779.7) pg/mg protein in controls (p = 0.006)." (PMID 16504044, 2006). "IGFBP-3 may also regulate senescence of alveolar epithelial cells and lung fibroblasts in emphysema." (PMID 30018981, 2018). "In the present study we found an increased staining for SA-β-Gal and a qPCR-confirmed upregulation of senescence-associated IGFBP-3 and IGFBP-rP1 in cultured primary parenchymal lung fibroblasts from patients with emphysema; this was supplemented by detection of higher protein levels of IGFBP-3." (PMID 16504044, 2006). "Furthermore, increased concentrations of IGFBP-3 were detected in cell culture supernatants of fibroblasts from patients with emphysema." (PMID 16504044, 2006). "In addition, IGFBP-3 levels were elevated in supernatants of fibroblast from emphysema." (PMID 16504044, 2006). "For IGFBP-3 and IGFBP-rP1 the upregulation in emphysema was confirmed by qPCR." (PMID 16504044, 2006). "In culture supernatants collected after 2 days of culture without fetal calf serum, IGFBP-3 was detectable in 8 samples of patients with emphysema and in 9 control samples." (PMID 16504044, 2006).
endothelial dysfunction (3 papers, 2014 to 2021). In vascular diseases, endothelial dysfunction is a systemic pathological state of the endothelium (the inner lining of blood vessels) and can be broadly defined as an imbalance between vasodilating and vasoconstricting substances produced by (or acting on) the endothelium. "The lower IGF-1 and IGFBP-3 and higher HOMA-IR levels in the Stressed group might further support inactivation or downregulation of retinal glia insulin receptors and subsequent endothelial dysfunction or glaucoma risk." (PMID 33670473, 2021).
esophagogastric junction adenocarcinoma (3 papers, 2019 to 2024). "IGFBP3 is identified as a biomarker with significant diagnostic value for early esophagogastric junction adenocarcinoma after ROC curve analysis and consistency index evaluation of the prediction value of line chart." (PMID 38302910, 2024).
fetal growth restriction (3 papers, 2013 to 2023). A fetus that does not grow beyond the 10th percentile of conventionally accepted weight for gestational age. "It was shown that the babies with intrauterine growth retardation showed relatively increased GH and low IGF-1 and IGFBP-3 concentrations, relatively low leptin, and increased ghrelin values." (PMID 24228030, 2013).
gestational diabetes (3 papers, 2016 to 2023). Carbohydrate intolerance first diagnosed during pregnancy. "In a prior study, higher IGF-I and IGFBP-3 concentrations in early gestation were associated with a higher risk of developing gestational diabetes during pregnancy." (PMID 38645676, 2023). "One study reported an inverse association between IGFI or IGFBP1 and risk for gestational diabetes; another reported a positive association between IGFI or IGFBP3 and risk for gestational diabetes." (PMID 27833901, 2016).
growth disorders (3 papers, 2013 to 2024). "Serum concentrations of IGF-I and IGFBP-3 are used clinically to examine growth disorders and to monitor treatment with GH." (PMID 38627922, 2024). "Measurement of exact IGF-1 and IGFBP-3 serum levels has been widely used as a screening parameter in the assessment of growth disorders." (PMID 27738609, 2016). "However, SNPs in two genes, IGFBP3 and SOS1, were common to both conditions, and these genes may have an impact on r-hGH sensitivity independent of the etiology of the growth disorder." (PMID 23761422, 2013).
hypertrophic cardiomyopathy (3 papers, 2022 to 2024). A condition in which the myocardium is hypertrophied without an obvious cause. "For instance, in hypertrophic cardiomyopathy patients with high Igfbp3 expression, immune cell infiltration was more enriched." (PMID 39769264, 2024).
juvenile idiopathic arthritis (3 papers, 2022 to 2025). Juvenile idiopathic arthritis (JIA) is the term used to describe a group of inflammatory articular disorders of unknown cause that begin before the age of 16 and last over 6 weeks. "In juvenile idiopathic arthritis (JIA), a similar trend of reduced serum IGF-1 or Insulin-Like Growth Factor Binding Protein 3 (IGFBP-3) levels in patients compared to controls was observed." (PMID 41383600, 2025).
leiomyoma (3 papers, 1997 to 2022). A well-circumscribed benign smooth muscle neoplasm characterized by the presence of spindle cells with cigar-shaped nuclei, interlacing fascicles, and a whorled pattern. "Low-grade leiomyosarcomas contained more IGF-II mRNAs than myometrium and leiomyoma, fewer type II IGF/mannose 6-phosphate receptors and less IGFBP-3 than myometrium and, in addition, fewer IGF-I mRNAs and type I IGF receptors than leiomyoma." (PMID 9184179, 1997).
leukemia (3 papers, 2019 to 2024). A malignant (clonal) hematologic disorder, involving hematopoietic stem cells and characterized by the presence of primitive or atypical myeloid or lymphoid cells in the bone marrow and the blood. "The subsequent occurrence of relapse in childhood leukemia was found to be inversely correlated with the rising levels of total IGFBP3 in a molecular mechanistic study." (PMID 38239636, 2023). "Both miR-196b and miR-1290 directly bind to the 3′UTR of insulin-like growth factor binding protein 3 (IGFBP3) and the downregulation of IGFBP3 is associated with the development of leukemia." (PMID 31126043, 2019).
medulloblastoma (3 papers, 2013 to 2023). A malignant, invasive embryonal neoplasm arising from the cerebellum. "It has been previously reported that IGFBP2 and IGFBP3 mRNA expression is elevated in medulloblastoma and correlates with poor prognosis." (PMID 37029430, 2023). "Expression of SerpinE1/PAI-1 (*1), Angiogenin (*2) and IGFBP-3 (*3) were notably low in medulloblastoma conditioned media, but SerpinE1/PAI-1 and IGFBP-3 were in fact present in BMEN1 cells." (PMID 27255663, 2016). "Relative to age- and gender-matched controls, median levels of IGFBP-3 were significantly higher in the CSF, but not blood, of children with medulloblastomas (p < 0.001)." (PMID 24400253, 2013).
metastasis (3 papers, 2016 to 2022). The spread or migration of cancer cells from one part of the body (where they first appeared) to another. "This study highlights the potential of vimentin-FBXL14 complexes as a therapeutic strategy to target EMT-induced metastasis disease, and the targeting vimentin by IGFBP-3 contributing to our understanding of the better means to control cancer metastasis." (PMID 33801272, 2021). "One study reported a significant increase in IGFBP3 levels in patients with tumor bone metastasis." (PMID 35845981, 2022). "For patients in N category, the OR was 3.211 (95% CI: 1.561–6.607, p = 0.002), indicating that the IGFBP-3 level in patients of N category whose tumor cells had lymph node metastasis were significantly lower than that in patients without lymph nodes in tumor cells." (PMID 27978831, 2016).
metastatic melanoma (3 papers, 2008 to 2014). A melanoma that has spread from its primary site to another anatomic site. "Primary and metastatic melanoma cell lines were grown to semi-confluence, transferred to a serum-free medium and treated with IGFBP-3 for 24 hours." (PMID 24905466, 2014). "In this study, we have investigated the effect of administering recombinant IGFBP-3 to cell cultures from primary and metastatic melanoma, from both human and murine sources." (PMID 24905466, 2014). "The median IGFBP-3 expression in metastatic melanoma specimens was 90%, slightly higher than its expression in primary tumors." (PMID 19025658, 2008). "Moreover, administration of IGFBP-3 in vivo to SCID mice inoculated with human metastatic melanoma cells strongly reduced or completely inhibited tumor growth." (PMID 24905466, 2014). "In vitro treatment with IGFBP-3 of human and murine metastatic melanoma cell lines specifically inhibited the cells' migratory and invasive behaviour, inducing up-regulation of melanocytic differentiation markers such as tyrosinase activity and melanin content." (PMID 24905466, 2014).
microcephaly (3 papers, 2012 to 2021). A congenital or acquired developmental disorder in which the circumference of the head is smaller than normal for the person's age and sex. "Multiple members of two unrelated families presented with progressive growth failure, moderate microcephaly, thin long bones, mildly decreased bone density and elevated circulating total IGF‐I, IGFBP‐3, and ‐5, acid labile subunit, and IGF‐II concentrations." (PMID 26902202, 2016). "Median (IQR) circulating levels of IGF-1 were higher in patients with severe microcephaly (162 ng/mL vs 129 ng/mL [to convert to nanomoles per liter, multiply by 0.131]; P = .01), but levels of IGFBP3 were not statistically significantly different." (PMID 33983398, 2021).
myocardial infarction (3 papers, 2020 to 2024). Gross necrosis of the myocardium, as a result of interruption of the blood supply to the area, as in coronary thrombosis. "In our study, DOCK6 rs737337 and rs17699089 interacted with IGFBP3 rs3110697 in relation to myocardial infarction diagnosis among HD patients." (PMID 36143124, 2022). "After an acute myocardial infarction, IGFBP-3 and IGF-1 levels significantly increased, which was associated with improved outcomes and echocardiographic parameters (LV dimensions, mass and ejection fraction)." (PMID 32831121, 2020). "In another study of acute myocardial infarction (n = 34, mean 34 y, 17% F), lower IGFBP-1 and higher easily dissociable IGF-I and IGFBP-3 levels were observed, compared to age- and sex-matched controls." (PMID 39595651, 2024). "IGFBP3 rs3110697, DOCK6 rs737337, and DOCK6 rs17699089 showed a gene–gene interaction concerning the diagnosis of myocardial infarction (TBA 0.63, p-value 0.032)." (PMID 36143124, 2022). "In males (n = 187, <60 y) with previous myocardial infarction, low total and not easily dissociable IGF-I, IGFBP-3, IGFBP-5 and ALS were associated with angiographically assessed coronary heart disease." (PMID 39595651, 2024).
non-alcoholic fatty liver disease (3 papers, 2018 to 2023). "In non-alcoholic fatty liver disease (NAFLD) and advanced fibrosis, it was shown that the levels of GH, IGF-1, and IGFBP-3 varied according to the severity of the steatosis, which differed from the variation in samples taken from patients with hepatitis C virus-related CLD." (PMID 29487568, 2018).
ovarian endometrioid carcinoma (3 papers, 2009 to 2014). "In our previous study, we found 51.4% of the ovarian endometrioid carcinoma (OEC) subtype showing lower IGFBP-3 expression, which is associated significantly with poor patient outcome." (PMID 20003326, 2009).
periodontal disease (3 papers, 2012 to 2022). "It was reported that high IGFBP-3 levels are associated with less periodontal disease in the general population." (PMID 23304536, 2012). "There is evidence that the severity of periodontal disease is related with decreased levels of IGFBP-3 in the blood." (PMID 36138609, 2022). "Similar variation was seen in terms of IGFBP-3 among various groups of periodontal disease severity." (PMID 35285598, 2022). "Since acromegalic patients probably had been exposed to elevated levels of IGF-I and IGFBP-3 over a decade, we expect them to present less periodontal disease compared to healthy subjects." (PMID 23304536, 2012). "Therefore, the present study aimed to evaluate salivary IGF-1, IGFBP-3, and CTX among children, adolescents, and younger adults and to determine the association of these markers among the study population with different chronological age groups with and without periodontal disease." (PMID 36138609, 2022). "The prime objective of this study was to estimate the salivary levels of IGF-1, IGFBP-3, and CTX among the participants with and without periodontal disease belonging to the different skeletal maturity groups, categorised according to cervical vertebrae staging criteria." (PMID 35285598, 2022).
periodontitis (3 papers, 2017 to 2022). An acute or chronic inflammatory process that affects the tissues that surround and support the teeth. "It was also found in SHIP data that low values of an IGF binding protein, IGFBP-3, were associated with increased levels of periodontitis." (PMID 28422991, 2017).
retinopathy of prematurity (3 papers, 2013 to 2022). A bilateral retinopathy characterized by neovascularization, scarring, retinal detachment, and eventually blindness. "Fat mass, fat-free mass, and percent body fat are differentially associated with adiponectin, IGF-1, and IGFBP3, so changes in these variables during the neovascular phase may alter retinopathy of prematurity risk." (PMID 31892145, 2019). "In the oxygen-induced retinopathy of prematurity model, insulin-like growth factor binding protein 3 (IGFBP-3) has antiapoptotic function on retinal endothelial cells." (PMID 35597446, 2022). "In the mouse model of retinopathy of prematurity, exogenous IGFBP3 promoted vessel survival during the vaso-obliterative hyperoxic phase and increased vessel regrowth during the relative hypoxic phase independent of IGF-1, and reduced apoptosis in retinal neurons." (PMID 23878504, 2013).
stomach cancer (3 papers, 2005 to 2016). "In addition, hypermethylation in the promoter of IGFBP3 was frequently detected in gastric tumor tissues." (PMID 24386080, 2013).